KRAS (KRas proto-oncogene, GTPase)
Diseases named in the same sentence as KRAS in open-access papers (continued):
Sharing a sentence is not in itself a finding about the gene and the disease.
pancreatic cancer (continued). "This is not sufficient to evaluate gossypol as a therapeutic reagent for pancreatic cancers, since approximately 90% of developing pancreatic cancer cells contain mutant KRAS." (PMID 35283426, 2022). "The attenuation of tumor growth was specific to pancreatic tumors that express oncogenic KRAS, suggesting that macropinocytosis is a critical KRAS-induced survival mechanism." (PMID 35147163, 2022). "Acquired therapy-resistance is a major concern nowadays, as it has been shown for KRAS-driven chemotherapy-resistant pancreatic cancers or KRASG12C-inhibitors in several KRAS-driven cancer types, for example." (PMID 36077838, 2022). "Recently, we also confirmed the feasibility of selectively targeting KRAS mutant pancreatic cancer with 70 kDa dextran-drug conjugates via both in vitro cellular studies and in vivo tumor model assessment." (PMID 35154489, 2022). "At that time, presence of mutated KRAS ctDNA sequences were identified in blood of patients with pancreatic cancer with KRAS mutant tumours [5••]." (PMID 35133615, 2022). "In particular, more than 90% of pancreatic ductal adenocarcinomas have KRAS mutations, which indicates the essential incorporation of aberrations in the RAS signaling pathway in pancreatic cancer." (PMID 35629212, 2022). "In this study, we aimed to explore the impact of trametinib and/or JQ1 on KRAS mutant pancreatic cancer and address the potential mechanism." (PMID 35468095, 2022). "In this context, Rigosertib, a compound that binds to the Ras-binding domain of multiple RAS effectors, has proven to inhibit tumour growth in KRAS-mutant colon and pancreatic cancer mouse models." (PMID 36138080, 2022). "Treatment with DEX-TP suppressed tumor progression in KRAS mutant pancreatic cancer orthotopic mouse models with reduced toxicity and significantly extended mouse survival time." (PMID 35154474, 2022). "For instance, miR-217 has been demonstrated to reduce expression of KRAS in pancreatic cancer cells." (PMID 35139853, 2022). "Lumakras (sotorasib), a novel KRAS G12C inhibitor, is being tested in clinical trials and has shown promising results in patients with advanced pancreatic cancer." (PMID 36284087, 2022). "It should be noted that BxPC3 cells are KRAS wild-type and thus represent a minority (5–10%) of pancreatic cancer cases." (PMID 35617275, 2022). "Previous reports have described that KRAS signaling can mediate the expression of cytokines such as IL-8 and GM-CSF in pancreatic cancer models." (PMID 35857848, 2022). "It has also been shown that pancreatic cancer infiltrating B cells can recognize mutant KRAS epitopes and can produce antibodies against KRAS presenting tumor cells." (PMID 36685537, 2022). "In our study, we observed that a subtype of KRAS-mutant pancreatic cancer cells with higher expression of TAP1 were more resistant to MEKi." (PMID 35806187, 2022). "The inhibition of the downstream transcription factor Fos-like antigen 1 (FOSL1) also seems to be a promising target in KRAS mutant lung and pancreatic cancers." (PMID 35883626, 2022). "In pancreatic cancer, tumor cells suffering ferroptosis can release KRAS, thus inducing immunosuppression and fatty acid oxidation in macrophages." (PMID 36552889, 2022). "Considering that the positive feedback loop is characterized by continuous activation, the research on feedback loops related to KRAS will help us better understand and explore its role in driving pancreatic cancer tumorigenesis." (PMID 35651786, 2022).
pancreatic cancer (continued). "Along similar lines, preclinical ERK inhibition of KRAS-mutant pancreatic cancer cell lines also showed MYC degradation and cellular suppression." (PMID 36284306, 2022). "We have previously demonstrated that GSK-3β gene expression is a target of oncogenic KRas signaling in pancreatic cancer cell lines and pancreas-specific deletion of GSK-3β in KRasG12D mice reduces cearulein-induced ADM and PanIN lesion development." (PMID 35646902, 2022). "To find transcription factors linked to oncogenic KRAS signal transduction in pancreatic cancer, we used primary pancreatic ductal epithelial cells and identified the AP1 transcription factor programs to be activated by oncogenic KRAS." (PMID 36534167, 2022). "Murine pancreatic cancer cells saw the functional modification of exosomes that carry a specific siRNA for targeting oncogenic KRAS, explaining the potential of these exosomes for treating the malignant tumors with identified molecular targets." (PMID 36059990, 2022). "Blockade of long-term ERK signaling also induces senescence through MYC degradation and p16 reactivation in KRAS-mutant pancreatic cancer." (PMID 35614034, 2022). "Drp1 deletion inhibits tumorigenesis of KRas-driven pancreatic cancer, but the role of mitochondrial dynamics in other Ras-driven malignancies is poorly defined." (PMID 36516772, 2022). "A significant reduction in tumor size (pancreatic cancer xenografts) in mice was observed after CRISPR-Cas13a-mediated KRAS G12D mRNA knockdown." (PMID 36359850, 2022). "In pancreatic cancer, the ablation of the oncogenic drivers mutant KRAS and c-MYC induces a dormant state, allowing the survival of a few residual cancer cells, which rely on autocrine IGF1/AKT as an adaptive mechanism." (PMID 35158815, 2022). "Pancreatic tumors reportedly harbor several gene aberrations, including those in KRAS, GNAS, and BRAF9–11." (PMID 35013462, 2022). "According to research about pancreatic cancer, KRAS-G12D emitted inside exosomes by ferroptotic cancer cells can be swallowed by macrophages." (PMID 35432535, 2022). "To address whether KRAS expression causes the transcriptional upregulation of DNA repair pathway components, in particular alt-EJ, we first conducted a microarray analysis of mouse Panc02 and human BxPC3 pancreatic cancer cell lines expressing either exogenous KrasWT or KrasMT." (PMID 36077614, 2022). "Our data together suggest that diet-induced inflammation plays a prominent role in inducing pancreatic neoplasm and is essential for licensing the adverse tumorigenic effect of oncogenic KRAS on pancreatic acinar cells." (PMID 35681705, 2022). "For example, one study has shown that treating KRAS-mutant pancreatic cancer patient-derived xenograft models with ERKi alone decreased tumor weight twofold compared to that of vehicle-treated controls." (PMID 35147163, 2022). "In the present study, we aimed to understand the role of extracellularly derived FAs in KRAS-driven pancreatic cancer." (PMID 34998392, 2022). "Activated KRAS was demonstrated to be a crucial regulator of macropinocytosis in a mouse pancreatic cancer model." (PMID 35177645, 2022). "Some of these strongly suppressed KRAS expression in Panc-1, pancreatic cancer cells, and reduced the tumor xenograft growth in immunodeficient mice, increasing also their median survival time by 70%." (PMID 36474260, 2022). "Decitabine is one such drug and was shown to be a potent growth inhibitor of KRAS-dependent pancreatic cancer cells and in patient-derived xenograft models." (PMID 36359850, 2022). "Oncogenic KRAS mutations, mainly G12D and G12V, are present in as high as 95% of pancreatic cancer patients and are critical for pancreatic cancer initiation and development; however, mutant KRAS alone is insufficient to drive PDAC in adults." (PMID 35681705, 2022).
pancreatic cancer (continued). "A phase I clinical trial has been undertaken to study the therapeutic effect of KRAS G12D siRNA delivered by mesenchymal stromal cell-derived exosomes in pancreatic cancer patients (NCT03608631)." (PMID 36015212, 2022). "For patients with the KRAS-G12D subtype of postoperative pancreatic cancer, more frequent follow-up times and more comprehensive and imaging examinations are necessary." (PMID 36582783, 2022). "Multiple developments in delivery formulations and the chemical structure of the oligonucleotides were made to enhance siRNA efficacy in targeting oncogenic KRAS in lung, colon, and pancreatic cancer cells." (PMID 35014625, 2022). "This regulatory loop utilizes the unique sustain subtype of the translation elongation factor eIF5A and the tyrosine kinase PEAK1 to increase KRAS protein synthesis in metabolic and energy demands of pancreatic cancer." (PMID 35651786, 2022). "LINC01420 is another KRAS-related lncRNA which is overexpressed in pancreatic cancer tissues and cell lines." (PMID 35139853, 2022). "UNIV TEXAS MD ANDERSON CANC CTR’s most-cited article reveals oncogenic KRAS-mediated reprogramming of glutamine metabolism in pancreatic cancer." (PMID 36505775, 2022). "LNAs were introduced at the 3'-ends of oligonucleotides mimicking G-quadruplex decoys in order to knockdown KRAS in pancreatic cancer cells." (PMID 36474260, 2022). "In summary, our findings show that blocking RAS downstream signaling and epigenetic pathway synergistically increases the antiproliferative activity in KRAS mutant pancreatic cancer cells." (PMID 35468095, 2022). "In our previous experiment, we found that KrasG12D-LOH exists in transgenic mice and human pancreatic cancer cells, wherein heterozygous PDAC cells lose their wild-type KRAS allele through mutation." (PMID 35743139, 2022). "The tumor-suppressor miRNA-126 (miR-126) is decreased in human breast and pancreatic cancers, resulting in increased pro-metastatic KRAS (Kirsten rat sarcoma viral oncogene homologue) levels 49-51." (PMID 36451861, 2022). "Studies have shown that pancreatic tumor cells exhibit low PFKM activity because of cellular O-GlcNAcylation, which leads to KRAS mutations." (PMID 35406597, 2022). "Recently, it has been reported that inhibition of the RAS-MEK-ERK signaling pathway induces protective autophagy in pancreatic cancer cells preventing the cytotoxic effects of KRAS pathway inhibition." (PMID 35468095, 2022). "A wealth of recent literature has identified that this is mediated predominantly by mutant KRAS (KRAS*), the oncogenic driver in most pancreatic tumors." (PMID 35815941, 2022). "Studies have shown that downstream malignant transformation by activated KRAS can promote the development of an immunosuppressive environment in pancreatic cancer, and silencing KRAS can reverse this altered immune microenvironment." (PMID 36358856, 2022). "KRAS has also been shown to promote SG formation following exposure of colon and pancreatic cancer cells to stress-inducing stimuli." (PMID 34294889, 2022). "Pancreatic cancer overall, and aggressive ovarian cancers in particular, harbor aberrant KRAS signaling correlating with more metastatic and progressive disease and poorer response to chemotherapies." (PMID 35216221, 2022). "Together, this research provides functional insights into the “open conformation” and validates three hits acting as pan-KRAS inhibitors to induce the apoptosis of pancreatic cancer cells." (PMID 36291766, 2022). "Together, the combined inhibition of the RAS downstream pathway and BET family proteins results in a potent synergistic antitumoral response to KRAS mutant pancreatic cancer cells." (PMID 35468095, 2022).
pancreatic cancer (continued). "More than 90% of human pancreatic tumors harbor genetic changes in the KRAS gene, resulting in constitutively active KRAS and consequent proliferative signaling." (PMID 35054996, 2022). "For example, in pancreatic cancer, KRAS promotes a shift in the glutamine pathway to support redox maintenance, as well as an increase in glycolysis to divert nutrients into the glycosylation and pentose phosphate pathways." (PMID 35681624, 2022). "This seems to be different to fully developed pancreatic cancer, where KRAS-induced NADPH oxidase signaling increases cellular superoxide and hydrogen peroxide levels." (PMID 35052641, 2022). "Mutant KRAS alone is insufficient to drive full-blown PDAC and pancreatic cancer risk factors as a second hit are required." (PMID 35681705, 2022). "Most PDAs express mutant KRAS5, so early efforts to understand metabolism in pancreatic cancer focused on the cell-intrinsic metabolic rewiring downstream of KRAS signaling." (PMID 36411320, 2022). "Along with KRAS mutation, loss of SMAD4 is a key event in pancreatic cancer progression and metastatic dissemination." (PMID 35326630, 2022). "EGF receptor signaling is important for pancreatic intraepithelial neoplasia (PanIN) and pancreatic cancer development induced by oncogenic KRAS." (PMID 35159011, 2022). "Taken together, these results showed an association between a high-m5C-score, mutation rates and transcriptional regulation of pancreatic cancer-related pathways, including the MAPK pathway doenstream of KRAS, and the TGFβ pathway." (PMID 36060802, 2022). "Compounds that stabilized the KRAS G4 in the FRET Melt2 assay were further tested in KRAS-dependent AsPc1 pancreatic cancer cells for their 72 h cytotoxicity and their correlating regulation of KRAS transcription." (PMID 36011352, 2022). "Mucin is one of the major culprits that hinder drug delivery, and several clinical studies identified that mucin is overexpressed in KRAS-driven pancreatic cancer in mouse and human models." (PMID 35409064, 2022). "The differentially expressed genes (DEGs) were compared between KRAS WT and KRAS G12D pancreatic cancer cell lines and TCGA patients." (PMID 35785187, 2022). "Our results of pan-cancer analyses found that KRAS mRNA expression is positively correlated with TMB in pancreatic cancer patients (P = 0.0072)." (PMID 34255132, 2022). "Recently, a study on the metabolism in pancreatic cancer has demonstrated that pancreatic cancer cells rely on the distinct pathway in which glutamine supports pancreatic cancer growth through a KRAS-regulated metabolic pathway." (PMID 35723350, 2022). "C-Myc is downstream of KRAS and interacts with several oncogenic and proliferative pathways in pancreatic cancer." (PMID 34978469, 2022). "Mitogen-activated protein kinase (MAPK) kinase (MEK) inhibitors show limited benefit in Kirsten rat sarcoma (KRAS) mutant pancreatic cancer due to drug resistance." (PMID 35806187, 2022). "engineered EVs to carry KrasG12D siRNAs or shRNAs to achieve direct and specific targeting to oncogenic KRAS in pancreatic cancer." (PMID 35915054, 2022). "have demonstrated that, the nuclear translocation of Lin28B, highly expressed in pancreatic cancer tissues, is promoted by KRAS through protein kinase C (PKCβ)." (PMID 35651786, 2022). "KRAS G12R is most commonly found in pancreatic cancer, totaling 15% overall in comparison to the more frequent G12D and G12V mutations." (PMID 34915443, 2022).
pancreatic cancer (continued). "The pharmacological dosage of FGF21 supplementation effectively inhibited pancreatic intraepithelial neoplasia lesions, inhibited liver metastasis, and prolonged the overall survival of KRAS-mediated pancreatic cancer under the high-fat-diet challenge." (PMID 36263162, 2022). "Based on the significant role of the KRAS mutation in pancreatic cancer, these results confirm the potential role of MIR31HG in the malignant transformation of different tumors, including KRAS-driven pancreatic cancer." (PMID 34489556, 2022). "Although oncogenic KRAS has long been considered to be constitutively active, and thus independent of upstream signals, a requirement for ADAM17 and ERBB1/EGFR in KRAS-induced pancreatic cancer has challenged this idea." (PMID 35971826, 2022). "Most interestingly, improvement of one of the compounds allowed us to obtain a peptidomimetic that decreased the survival of pancreatic cancer cell lines harbouring oncogenic KRAS." (PMID 36138080, 2022). "This tumor suppressive miRNA has been shown to target KRAS in colorectal and pancreatic cancer cells." (PMID 35139853, 2022). "The protein expression levels of MYEOV, GPRC5A, and KRAS showed a consistent trend in pancreatic cancer tissues and normal tissues adjacent to pancreatic cancer from three pancreatic cancer patients." (PMID 36358856, 2022). "This study illuminated a therapeutic strategy of combined targeting of the KRAS pathway and mitochondrial respiration to treat pancreatic cancer." (PMID 36263211, 2022). "More than 90% of patients with pancreatic cancers have KRAS mutations, and BRAF deletion mutations are mutually exclusive with KRAS mutations." (PMID 35804932, 2022). "For pancreatic cancer with a distinct cell context, for example, driven by KRAS or CDK, pevonedistat exhibits a similar anticancer effect and mechanism." (PMID 35155257, 2022). "In the present study, we aimed to understand the role of extracellularly derived fatty acids in KRAS-driven pancreatic cancer." (PMID 34998392, 2022). "Given that KRAS mutations are almost ubiquitous to PDAC, the National Cancer Institute has identified the development of anti-KRAS therapies as one priority for pancreatic cancer research." (PMID 35159234, 2022). "ARL4C was identified as RAF1-MEK/ERK pathway-dependent gene in ameloblastoma cell proliferation and osteoclast formation and as down localization of KRAS in pancreatic cancer." (PMID 35785187, 2022). "Studies in pancreatic ductal adenocarcinoma (PDA) rodent models indicated that KRAS favors immune escape in pancreatic cancer cell-bearing mice by activating the BRAF and MYC axis." (PMID 35508982, 2022). "EVI1 as a universal oncoprotein in pancreatic cancer has been shown to up-regulate KRAS levels via suppression of miR-96." (PMID 35139853, 2022). "Using orthotopic pancreatic cancer mouse models, it was demonstrated that exosomes carrying KRAS specific siRNA can suppress tumor growth, inhibit metastasis, and improve overall survival." (PMID 35328535, 2022). "As KRAS mutation was found in 70~95% of PDAC patients, researches on the regulation of autophagy in Ras-expressing pancreatic cancer cells were rapidly increasing." (PMID 36263211, 2022). "miR-96 is another tumor suppressor miRNA which directly targets the KRAS in pancreatic cancer cells." (PMID 35139853, 2022). "In particular, in NSCLC carrying mutant KRAS cells are sensitive to glucose deprivation or treatment with metformin, an inhibitor of mitochondrial complex I and of pancreatic cancer cell respiration." (PMID 36048281, 2022).